IL6 (interleukin 6)
Diseases named in the same sentence as IL6 in open-access papers (continued):
Sharing a sentence is not in itself a finding about the gene and the disease.
cancer (continued). "Our studies demonstrate that PR protein levels are decreased in cancer associated stroma and that PR exerts inhibitory impacts to PCa cell mobility through modulating the expression of two important cytokines, SDF-1 and IL-6." (PMID 24664419, 2014). "Interleukin 6 (IL-6) is also an important cytokine that can stimulate the Janus Kinases/Signal Transducer and Activator Transcription 3 pathway in cancer cells." (PMID 24664419, 2014). "We then correlated the cachectic parameters analyzed with survival in 19 patients with stage IIIB or IV cancer who received supportive care after IL-6 evaluation." (PMID 25010770, 2014). "Advanced cancer patients had similar numbers of circulating myDC to cancer-free patients and healthy individuals, and secreted similar levels of IL-1β, IL-6, IL-10, IL-12 and IL-23." (PMID 23901045, 2014). "The indirect pro-angiogenic effects are for instance related to the secretion of interleukin-6 by MSC that induces endothelin-1 production by cancer cells and thereby enhances endothelial cell recruitment and activation." (PMID 25222747, 2014). "In experimental models, IL-6 showed induction of cancer stem cells and epithelial-mesenchimal transition phenotype, which are possible condition for resistance to the anti-HER-2 compounds trastuzumab and lapatinib." (PMID 24886605, 2014). "STAT3, a tightly regulated transcription factor, is activated upon phosphorylation in response to IL-6 and has been shown to be present in a number of cancers." (PMID 25460165, 2014). "Accordingly, we believe that tocilizumab is useful for the treatment of cachexia induced by IL-6 over-expressing cancer." (PMID 25010770, 2014). "miR-155 transcription is induced by TGF-β, interferon-γ (IFNγ), and interleukin-6 (IL-6) and influences numerous cancer cell signaling pathways to promote tumorigenesis." (PMID 25717380, 2014). "Circulating level of IL-6 is known to be important for keeping body weight and for survival in cancer patients." (PMID 24963216, 2014). "For example, both paracrine and autocrine IL-6 signaling activates NF-κβ in cancer cells, and there is substantial crosstalk between NF-κβ and STAT3, leading to their positive or negative regulation." (PMID 24722453, 2014). "Our results are in accordance with a context in which IL-6 can play a prominent role in the cancer-induced muscle wasting." (PMID 24967341, 2014). "Recently we studied if the capacity of metastatic cells to overproduce IL-6 is regulated by cancer cell-independent mechanisms." (PMID 24802641, 2014). "Targeting IL-6 signaling pathway in cancer therapy is supported by a numerous preclinical and translational observations." (PMID 24670367, 2014). "A significant positive correlation was observed in the cancer specimen that stained positively for DNMT3b and IL-6." (PMID 24625449, 2014). "In order to see if this epigenetic switch is relevant for human cancers, Iliopoulos and coworkers examined the expression levels of IL6 and Let-7 in cancer and normal breast, prostate, hepatocellular, and lung tissues." (PMID 24499937, 2014). "Constitutive activation of NF-κB, the major pathway that regulates immune inflammatory responses and produces pro-inflammatory cytokines, such as TNF-α, IL-1β, and IL-6, leads to chronic inflammation, which promotes cancer." (PMID 24670367, 2014). "Collectively, these data suggest that constitutive IL-6 release drives IDO expression in human cancers via STAT3." (PMID 24657910, 2014). "On one side, IL-6 and other pro-inflammatory cytokines are involved in the mechanisms that promote cancer cachexia." (PMID 24886605, 2014). "The Colon-26 (C26) carcinoma is a well-established murine model of cancer cachexia resulting in high systemic levels of IL-6." (PMID 24667661, 2014). "Since the cloning of IL-6 cDNA, IL-6 has been proved to be produced in varied kinds of cells, including cancer cells, in addition to T- cell." (PMID 24664372, 2014).
cancer (continued). "This activity is termed “IL-6 trans-signaling” and plays a critical role in promoting chronic inflammation and inflammation related cancer." (PMID 25093140, 2014). "Blocking PR expression by siRNA or supplementation of exogenous SDF-1 or IL-6 to conditioned media from PR positive stromal cells counteracted the inhibitory effects of PR to cancer cell migration and invasion." (PMID 24664419, 2014). "On the other hand, prolonged production of IL-6 and GM-CSF and activation NF-κB pathway can exacerbate the inflammation and induce cancer progression through intensifying angiogenesis and inhibition of transformed cells apoptosis." (PMID 25117071, 2014). "Some inflammatory cytokines are consequent on long-term interplay of immune and cancer cells, such as prostaglandins, IL-1β, IL-6, and IL-13, which can trigger the expansion and activation of MDSCs." (PMID 25937967, 2014). "The results showed weak vimentin expression but strong E-cadherin expression in low IL-6-expressing cancer tissues, whereas strong vimentin expression but weak E-cadherin expression was observed in high IL-6-expressing cancer tissues." (PMID 24789104, 2014). "In fact, several drugs targeting this pathway are in development or used in the clinic for the treatment of cancer including neutralizing anti-IL-6 antibodies and small molecule or peptide inhibitors of STAT3 and/or JAK2." (PMID 24657910, 2014). "The addition of the IL-6 and IL-8 antibodies to the coculture system of TAMs and LoVo-P cells reduced the number of invasive cancer cells in a dose-dependent manner; an isotype-matched IgG at 10 μg/ml did not have similar effects." (PMID 24885636, 2014). "Regarding the mechanism of the hypercoagulability state in cancer patients, tumor necrosis factor, interleukin-1 and interleukin-6, which are released by monocytes or macrophages, lead to endothelial damage." (PMID 25103421, 2014). "Cancer cells expressing jagged-1 activate Notch signaling in OB and stimulate the secretion of IL-6." (PMID 25147739, 2014). "C1QTNF4 is an inflammatory cytokine capable of activating both Stat3/IL6 and NF-κB pathways, as shown in cancer cells." (PMID 24743338, 2014). "Others have reported significant increases in IL-6 after chemotherapy administration in cancer patients." (PMID 25254959, 2014). "In particular, IL-6 is an inflammatory cytokine released by T cells, macrophages and several cancer cell types." (PMID 25322805, 2014). "The high level of IL-6 in such a chronic inflammation-related cancer possibly stimulates miR-21 expression, and RAS activation is partly correlated with let-7a down-regulation." (PMID 25184951, 2014). "JAK2/STAT3 is one of the major signaling pathways triggered by IL-6 and is constitutively activated in numerous cancer cell lines and types, including GC tissues." (PMID 24527098, 2014). "We identify that SDF-1 and IL-6 are the two important genes, which mediate repressive actions of stromal PR to cancer cells." (PMID 24664419, 2014). "Here we show that these FBEs are necessary for Cebpb promoter activation in skeletal muscle in response to IL-6, a predominant cytokine in the C26 model of cancer cachexia." (PMID 25539728, 2014). "Among them, IL-6 secretion of senescent MSCs was dramatically increased by 40 fold compared with young MSCs, strongly suggesting that IL-6 was involved in the ability of senescent MSCs to promote cancer cell growth and migration." (PMID 25419563, 2014). "Because STAT3 can also be phosphorylated by the IL-6 signaling cascade and because IL-6 is one of the most ubiquitously deregulated cytokines in cancer, it is a rational biological target for therapeutic investigations." (PMID 25268165, 2014). "IL-6 is a pleiotropic cytokine with a wide range of biologic actions in acute and chronic inflammation, vascular disease, and cancer, and serum and BAL IL-6 levels are correlated with ARDS mortality." (PMID 25100435, 2014).
cancer (continued). "In clinic, the serum levels of VEGF, IL-8 and IL-6 have been suggested as potentially predictive markers for survival in cancer patients under sunitinib." (PMID 24555849, 2014). "Eight out of 15 different kinds of cancer cell lines show Lin28B overexpression, let-7 downregulation, and high levels of IL6." (PMID 24709904, 2014). "Plasma levels of ACTH and corticosterone (the main circulating glucocorticoid in rodents) were similar in all malignant cell types (control or iB16-shGCR), whereas circulating levels of IL-6 decreased in mice bearing iB16-shGCR cancer cells." (PMID 24802641, 2014). "This resulted in the reduction of IL-6 and IL-8 and a concurrent reduction in the number of invasive cancer cells." (PMID 24885636, 2014). "They showed that cancer tissues have higher levels of IL6 and lower levels of Let-7 as compared to normal tissues." (PMID 24499937, 2014). "As expected, some cytokines showed significant differences between healthy donors and pretreated cancer patients (IL-1β, IL-2, IL-6, TNF-α, and MCP-1)." (PMID 24800238, 2014). "Instead, Gattelli and colleagues show that fulvestrant induces cancer cells to produce IL-6, resulting in increased RET expression and thus creating a feed-forward RET–IL-6 expression loop." (PMID 24467886, 2014). "The results of our tests proved that the crude GpEPS preparation exhibited antitumor activity against carcinoma cells (lines SiHa) and stimulated production of Il-6 and TNF-α by macrophage line THP-1." (PMID 25114920, 2014). "The outcome of activation of MDSC by metastasizing cancer cells in vitro can be summarized as exaggerated augmentation of IL-6 production by MDSCs." (PMID 24021059, 2013). "A significant upregulation of the circulating IL-6 was found in the cancer patients, particularly in the advanced-staged individuals, than the healthy controls." (PMID 23658720, 2013). "IL-6 is one of the most common cytokines in cancer, and it is overexpressed in patients with metastatic renal carcinoma." (PMID 23690956, 2013). "The results showed that IL-6 mRNA was induced in fibroblasts when stimulated with cancer cell–conditioned media." (PMID 23593346, 2013). "Consistent with previous findings, we showed the enhancement of IL-6 mRNA in EFGR-TKI-treated cancer cells." (PMID 23592411, 2013). "Cox proportional hazard regression models showing baseline IL-6 and sTNFR2 independently predicted incident cancers." (PMID 24205276, 2013). "In the present study, we showed that IL-6 deficiency attenuated the expression of CD44 in in vivo gastric tumorigenesis model, suggesting the relationship among IL-6, CD44, and cancer stem cells." (PMID 23593346, 2013). "We found that EGFR-TKI treatment in cancer cells increased IL-6 secretion, even if EGFR phosphorylation was completely blocked by EGFR-TKI." (PMID 23592411, 2013). "The NF-κB pathway plays a central role in the regulation of immune responses and targets several inflammatory cytokines, such as TNF-α, IL-1, IL-6 and IL-8 and its aberrant activation has been identified in many cancer types." (PMID 23526956, 2013). "Because IL-6 strongly induces the growth and invasion of cancer cells, previous studies were focused on the relationship between IL-6 and anti-cancer treatment." (PMID 23592411, 2013). "We demonstrate invitro evidence suggesting that IL-6 from cancer cells induces acute interstitial pneumonia as one of mechanisms responsible for the occurrence of a side effect of EGFR-TKI treatment." (PMID 23592411, 2013). "Their interactions with OCCs seemed mediated by IL6, which has been described determinant for cancer migration and infiltration mechanisms." (PMID 23369187, 2013). "For example abnormally increased levels of IL-6 are involved in systemic inflammatory response with impact on outcome and postoperative complications, and even on prognosis and mortality in cancer patients." (PMID 24472144, 2013).
cancer (continued). "In such cells, we unravel the generalized involvement of the beta-catenin-driven machinery in the stabilization of EGF-induced mRNAs, including the cancer stem cell regulator IL6." (PMID 24260469, 2013). "Other studies also reported that antioxidants dose-dependently inhibit inflammatory markers like TNF-α, IL-6, and IL1β gene expression in the cells of chronic diseases and their release from a human cancer cell line." (PMID 23365614, 2013). "Elevated circulating levels of inflammatory biomarkers, i.e., IL6, TNFα, C-reactive protein (CRP), have been associated with a greater risk for several types of cancer and cancer prognosis, including breast." (PMID 23991131, 2013). "In contrast, the fibroblasts secreted 5–600 times more IL-6 when treated with cancer cell–conditioned media." (PMID 23593346, 2013). "Cytokines such as monocyte chemoattractant protein-1 (MCP-1), IL-6, and matrix metalloproteinases have been suggested to promote cancer progression." (PMID 23552194, 2013). "IL-6 has been found to play important role in cell migration, invasion, proliferation, apoptosis, angiogenesis and differentiation in cancer cells." (PMID 23690956, 2013). "Molecular analyzes in epidermal fibroblasts demonstrated disturbances to the expression profile of core circadian clock genes and elevated expression of the proinflammatory cytokines IL-6 and TNF-α, known to be risk factors in cancer and metabolic disorders." (PMID 24146819, 2013). "IL6 blood serum levels, for example, steadily go up as incurable cancers become more life-threatening." (PMID 23303309, 2013). "Taken together, these results clearly showed that QYHJ reduced TAM infiltration and inhibited IL-6 expression, eventually suppressing cancer-related inflammation." (PMID 23922983, 2013). "Because IL-6 has been suggested to contribute to the development or progression of acute interstitial pneumonia, we anticipated the possible linkage between IL-6 from cancer cells and EGFR-TKI-induced acute interstitial pneumonia." (PMID 23592411, 2013). "Serum TNF-α and IL-6 increased otherwise in the group with severe cancer when compared to those of control, whereas IL-1β still kept steady among groups." (PMID 23349693, 2013). "The highest values of IL-6 were obtained in patients with early cancer (more than 8-fold increase), which seems to confirm the presence of acute inflammation in these patients." (PMID 23554823, 2013). "IL-6 has also been reported to influence invasiveness and metastasis in various experimental models, suggesting its involvement in cancer progression." (PMID 23593346, 2013). "Along with the progression of the disease, there was observed a decrease in the production of proinflammatory cytokines, and the lowest IL-6 values were obtained in patients with cancer metastases (more than 3-fold increase)." (PMID 23554823, 2013). "Generally cancer cells are a source of inflammatory cytokines and growth factors (IL-1β, IL-3, IL-6, IL-11, IL-23, and TNF-α)." (PMID 23554823, 2013). "Amongst all the STATs signals, persistently activated STAT3 via IL-6 induced JAK2 activation promotes cancer cell proliferation, survival and invasion by promoting pro-oncogenic inflammatory pathways." (PMID 23690956, 2013). "While our study was the first prospective study examining the effects of the adipokines on cancer development in Chinese population, our findings on IL-6 and sTNFR-2 were in line with those of western cohorts." (PMID 24205276, 2013). "Inadequate neutralisation of other cytokines due to a protein carrier effect has been reported in the literature and included situations in which there is a high target load, for example, IL-6 in cancer patients." (PMID 24286335, 2013). "Increased IL-6 in LNCaP-IL-6+ cancer cells showed a growth advantage, STAT3 activation, high expression of VEGF association with androgen-independent growth." (PMID 23806095, 2013).
cancer (continued). "The highest values of IL-6 were obtained in early cancer (more than 8-fold increase), which seems to confirm the presence of acute inflammation." (PMID 23554823, 2013). "Several inflammatory mediators, such as TGFβ and IL-6, have been demonstrated that contribute to the invasion and metastasis of cancers." (PMID 23431386, 2013). "Higher levels of IL-6 and EGFR in HNSCC cancer patients’ serum are found to be associated with a higher second primary cancer (SPC) specific mortality and hence established as serum biomarkers for HNSCC." (PMID 23414419, 2013). "In humans, prospective epidemiological studies have also reported the association of high levels of interleukin-6(IL-6), tumor necrosis factor-alpha (TNF-α) and A-FABP, and low level of adiponectin, with cancer development." (PMID 24205276, 2013). "IL-6 is a multifunctional cytokine that supports cancer cell proliferation and inhibits apoptosis through activation of STAT3." (PMID 23374147, 2013). "Our results agree with previous studies showing that blocking IL-6 attenuates cancer cell invasiveness through down regulation of MMP-2 and MMP-9 expression." (PMID 23593315, 2013). "On the other hand, EGFR-TKI activates AP-1 in cancer cells and produces a large amount of IL-6 while growth inhibition is observed." (PMID 23592411, 2013). "As Syndecan-1 modulates the cancer stem cell phenotype via regulation of the Wnt and IL-6/STAT3 signaling pathways, it emerges as a promising novel target for therapeutic approaches." (PMID 24392029, 2013). "The cancer cell–conditioned media alone did not explain the observed increase in IL-6 levels, because the IL-6 concentration was about 0.5 ng/mL in cancer cell–conditioned media from SH101 cells and undetectable in the other cell lines." (PMID 23593346, 2013). "IL-6 is a major activator of STAT3 signaling and it is associated with poor prognosis in different cancers." (PMID 24146823, 2013). "Chemotherapy drugs that depend on Mcl-1L- or IL-6-related signaling should be considered carefully before use in patients undergoing hepatectomy for malignant tumor resection." (PMID 23825534, 2013). "EC perlecan silencing significantly changed this regulatory relationship, eliminating the ability of ECs to inhibit cancer cell invasiveness via increased interleukin-6 secretion." (PMID 24037645, 2013). "Direct inhibition of myeloid DC differentiation mediated through IL-10 and IL-6 was proposed to induce a potentially immunocompromising microenvironment in cancer patients." (PMID 23616009, 2013). "The biological effect of SNP IL-6–174 G>C in relation to promotion of cancer progression is consistent with the observed decreased survival time." (PMID 24204677, 2013). "Based on the detrimental consequences of IL-6 activity in ovarian cancer including induction of chemoresistance and malignant ascites formation, targeting IL-6 and its receptor system is considered as an emerging therapeutic approach for cancer chemotherapy." (PMID 23593315, 2013). "In this study, their highest levels of IL-23, like IL-6, were obtained in patients with early cancer, while the lowest value of both these cytokines was obtained in patients with disseminated cancer." (PMID 23554823, 2013). "There is a growing area of research asserting that cancer- and cancer-treatment related fatigue is driven by pro-inflammatory cytokines (e.g., IL-6, IL-1β, TNF-α) and inflammatory pathways (e.g., CRP, IL-1RA) as observed using animal and clinical models." (PMID 23959120, 2013). "In summary, we show that IRF9 protein expression is increased in human PCa and correlates with IL6 expression in cancer areas." (PMID 23913484, 2013). "IL-6 signaling in cancer cells themselves imbued them with cancer stem cell properties and epithelial-to-mesenchymal transition (EMT) phenotypes, which facilitate cancer cell invasion into the surrounding tissue and blood vessels, and cause distant metastasis." (PMID 24021059, 2013).